NRAS (NRAS proto-oncogene, GTPase)
Diseases named in the same sentence as NRAS in open-access papers (continued):
Sharing a sentence is not in itself a finding about the gene and the disease.
melanoma (continued). "In summary, our findings identify the mutually exclusive NRAS and BRAF mutation status as possible predictive marker for the response to DNA synthesis inhibitors such as antifolate drugs in melanoma patients." (PMID 24941944, 2014). "Further analysis revealed that the growth-inhibitory effects mediated by DTIC were rather due to interference with nucleotide salvaging, and that NRAS mutant melanoma cells exhibit higher activity of the nucleotide synthesis enzymes IMPDH and TK1." (PMID 24941944, 2014). "BRAF inhibitors, such as vemurafenib and dabrafenib, demonstrate clinical benefit in melanomas harboring the BRAF p.V600E mutation and MEK inhibitors act in the presence of BRAF and NRAS mutations." (PMID 24959217, 2014). "The phase I/II trial NCT01781572 with MEK inhibitor MEK162 and CDK inhibitor LEE011 for NRAS-mutant melanoma is ongoing." (PMID 24743024, 2014). "The present study has expanded the detailed molecular analysis of clinical stage III melanoma by the characterization of BRAF and NRAS mutations in a homogeneous group of patients with regional nodal macrometastases." (PMID 24959217, 2014). "We designed our study to analyze changes in NRAS mutant tumor cells derived from malignancies other than melanoma." (PMID 25277205, 2014). "The most commonly observed oncogenic events in melanomas are activating mutations in the BRAF and NRAS proto-oncogenes, which occur in 70% of cases." (PMID 24550252, 2014). "Usage is additionally hampered by frequent occurrence of heterogeneity in melanoma with respect to NRAS and BRAF status, leading to a substantial discordance in mutation status in these genes in a primary compared to the metastases." (PMID 25593912, 2014). "Recent studies have shown that a dual inhibition of MAPK and PI3K/AKT/mTOR pathways leads to a reduction of cell viability in vitro and a decrease in tumor size in xenograft models of NRAS mutant melanoma." (PMID 25277205, 2014). "The search for driver mutations in melanoma continues, with the previously identified subtypes involving BRAF, NRAS, KIT, GNAQ, and GNA11 expanded recently to include NF1 and telomerase." (PMID 24743024, 2014). "In the majority of human melanomas, the mitogen-activated protein kinase (MAPK) pathway is constitutively activated by oncogenic mutations in NRAS or BRAF." (PMID 25422890, 2014). "β-catenin suppresses expression of p16INK and cooperates with NRAS in transformation to a frank melanoma." (PMID 24743024, 2014). "We found no substantial differences in the levels of ERK1/2, MEK1/2, BRAF, NRAS between the horse and human melanoma cells." (PMID 25413220, 2014). "The efficacy of SCH772984 in NRAS-mutant and double wild-type melanoma was also striking with the majority being highly sensitive." (PMID 25142146, 2014). "Accordingly, treatment of NRAS-mutant melanoma cell lines with an inhibitor targeting multiple kinases including Axl, leads to growth arrest and apoptosis." (PMID 25344858, 2014). "Our current study aimed to elucidate the effects of different targeted inhibitors and their combinations in non-melanoma NRAS mutant tumor cells." (PMID 25277205, 2014). "SCH772984 is highly active amongst BRAF-mutant, NRAS-mutant, double mutant and double wild-type melanoma cell lines, and this drug potently inhibited some lines with innate resistance or acquired resistance to vemurafenib." (PMID 25142146, 2014). "In this study, we perform small RNA profiling and identify miR-146a as an oncogenic BRAF- and NRAS-regulated miRNA that promotes the initiation and progression of melanoma." (PMID 24550252, 2014). "Treatment of BRAF-mutant and NRAS-mutant melanoma lines with WNT3A and the MEK inhibitor AZD6244 induces apoptosis." (PMID 24743024, 2014).
melanoma (continued). "Nazarian and co-workers also demonstrated reactivation of NRAS signaling in PLX4032-refractory melanomas leading to MAPK pathway reactivation and disease progression." (PMID 24885200, 2014). "This study provides evidence that NRAS mutant cancer shares signaling similarities across different malignancies, thus opening up potential treatment options comparable to those proven to be effective in NRAS mutant melanoma tumors." (PMID 25277205, 2014). "To examine the antiproliferative effects of CH5126766 or PD0325901, we used two melanoma cell lines with mutations resulting in ERK activation, SK-MEL-28 (BRAF V600E), and SK-MEL-2 (NRAS Q61R)." (PMID 25422890, 2014). "XL888 was effective against NRAS mutant melanoma cells in vitro and in xenografts, most likely by decreasing protein levels of AKT, CDK4, and WEE1." (PMID 24743024, 2014). "Oncogenic mutations of the NRAS gene in codons 12, 13 and 61 lead to increased downstream signaling through the well-known NRAS mutant melanoma signaling cascades MAPK and PI3K/AKT/mTOR." (PMID 25277205, 2014). "Trials are testing different drugs and their combinations in NRAS mutant melanoma patients (NCT01781572; NCT01941927)." (PMID 25277205, 2014). "Accordingly, we find that BRAF and NRAS mutant melanoma cell lines and short-term melanoma cultures show higher levels of miR-146a compared to those that are wild type for these genes." (PMID 24550252, 2014). "All three (100%) BRAF/NRAS double mutants, 11 of 14 (78%) NRAS mutants and 5 of 7 (71%) wild-type melanomas were sensitive." (PMID 25142146, 2014). "For BRAF and NRAS wild-type melanoma cell lines, all seven were sensitive to ERK inhibition, with six of seven highly sensitive to SCH772984, including M418, which is a KRASG12A mutant." (PMID 25142146, 2014). "As expected, this list included well documented frequent oncogenic drivers of melanoma, including hotspot mutations in BRAF, NRAS, RAC1, PPP6C, TRRAP, MAP3K5 and BCL2L12." (PMID 24913145, 2014). "Signaling changes after incubation with inhibitors were studied and compared to those found in NRAS mutant melanoma." (PMID 25277205, 2014). "50% of melanomas harbour activating mutations in the kinase BRAF, the most common being a V600E substitution, and 25% harbour mutations in the GTPase NRAS." (PMID 24941944, 2014). "Combined targeting of MEK and PI3K was superior to MEK and mTOR inhibition in NRAS-mutant melanoma cell lines and xenografts." (PMID 24743024, 2014). "We also performed deep sequencing of somatic mutations that uncovered the clonal structures of melanomas, helped to dissect diverse mutational mechanisms in subclones, and further established the initiation roles of BRAF and NRAS mutations in melanoma." (PMID 25393105, 2014). "Acquired resistance to B-RAF inhibitors has been reported to primarily result from MAPK reactivation, driven by secondary mutations in NRAS and MEK1 genes in a subset of melanoma patients." (PMID 25074438, 2014). "We investigated the interaction between genes within our 200-gene signature with the four known melanoma ‘driver’ genes (i.e., NRAS, BRAF, MITF and cKIT)." (PMID 23638386, 2013). "Melanomas are characterized by mutation in NRAS (20% of tumors), and BRAF in about 50% of cases, and are different subpopulations in melanomas cases." (PMID 23984088, 2013).
melanoma (continued). "For successful translation into clinics it will be essential to test more NRAS mutant cell lines for the activity of inhibitor combinations and to refine and fully characterize the genetic profile of melanoma cells that are most likely to respond." (PMID 23660168, 2013). "Of the three melanoma subtypes analyzed in considerable numbers (SSM, NM, ALM), percentages of BRAF and NRAS mutations combined were highest in SSM reaching 82%, lower in NM with 67% and lowest in ALM with 46%." (PMID 23694694, 2013). "Of the melanoma patients treated with Sunitinib, 11% had mutations in KIT [other patients presented with mutations in BRAF (23%), NRAS (14%), or GNAQ (0%)]." (PMID 23515890, 2013). "NRAS and PTEN mutations were first reported to be mutually exclusive in melanoma, which is likely explained by their ability to share the same signaling pathway." (PMID 24416617, 2013). "Overall, mutations were detected in 49% primary melanomas and 51% metastases, for BRAF gene, and 15% primary tumors and 16% secondaries, for NRAS gene." (PMID 23987572, 2013). "In this single institution study, we correlated mutation status and expression levels of BRAF and NRAS to dacarbazine (DTIC) treatment response as well as progression-free and overall survival in a cohort of 85 patients diagnosed with advanced melanoma." (PMID 23673558, 2013). "New Zealand has a high incidence of melanoma and it was therefore of interest to compare the frequencies of activating BRAF and NRAS mutations in New Zealand-derived melanoma lines with published values." (PMID 23658559, 2013). "Despite, being a highly relevant therapeutic target, design of small molecules selectively inhibiting mutant NRAS in melanoma, to date, remains an unsolved challenge." (PMID 23660168, 2013). "Further studies are warranted to confirm a potential predictive and prognostic role of BRAF and NRAS expression levels in advanced melanomas." (PMID 23673558, 2013). "In conclusion, we present data linking BRAF, as well as NRAS, mRNA expression levels to outcome in advanced melanoma." (PMID 23673558, 2013). "To gain a more profound understanding in the role of BRAF or NRAS mutations in the development of melanoma from nevi we compared the genotype and BRAFV600E protein expression of melanomas and their associated nevi with control nevi of the same patient." (PMID 23861977, 2013). "In 2012 an inducible mouse model of NRAS mutant melanoma and network modelling established the in-vivo therapeutic syngeristic efficacy of targeted inhibition of CDK4 and MEK to decrease melanoma survival and proliferation." (PMID 24216705, 2013). "It is to date the most promising strategy to interfere with currently undrugable targets such as mutant NRAS in melanoma." (PMID 23660168, 2013). "Noteworthy, PPP6C mutations were more frequent in melanomas that were mutated for both BRAF and NRAS, while RAC1 mutations were more frequent in melanomas that were wild-type for both BRAF and NRAS." (PMID 24416617, 2013). "We examined five melanoma lines, three of which were BRAF- and two NRAS-mutated, and four colon carcinoma lines, of which three were KRAS- and one BRAF-mutated." (PMID 22869096, 2012). "While BRAF mutations represent the most frequent oncogenic alteration in melanomas so far (BRAFV600E in up to 70% of cases), NRAS mutations occur in 15 to 30%." (PMID 22535842, 2012). "Among the up-regulated oncogenes in melanoma, ABL2, NRAS, PDGFC and FGF1 have been reported to be melanoma-associated oncogenes." (PMID 22295108, 2012). "In primary melanoma, mutations in RAS and RAF are mutually exclusive, but after vemurafenib treatment failure, it was identified a new mutation in the NRAS kinase, causing the reactivation of the MAPK pathway and disease progression." (PMID 22216021, 2012).
melanoma (continued). "In humans, NRAS and BRAF genes are mutated in 15% to 30% and in 50% to 70% of human melanomas, respectively, leading to their permanent activation followed by promotion of proliferation, survival, invasion, and angiogenesis of melanoma." (PMID 22013435, 2012). "We have tested a battery of melanoma and colon carcinoma cell lines that carry mutations in BRAF, NRAS and KRAS genes and have observed that those with NRAS and KRAS mutations are more sensitive to killing by IPA3." (PMID 22869096, 2012). "Directing this test to a single disease, 90 of 150 (60%) melanomas from sites throughout the body harbored a mutation tested, including 57, 23, 6, 3, and 2 mutations in BRAF, NRAS, GNAQ, KIT, and CTNNB1, respectively." (PMID 22536370, 2012). "Models VARI-LTM-044 colorectal cancer and VARI-LTM-034 pancreatic cancer both had a single KRAS mutation; melanoma models VARI-LTM-086 and VARI-LTM-027 had BRAF and NRAS mutations, respectively." (PMID 22709571, 2012). "The melanoma models used in our study were derived from both primary and metastatic sites (including skin, lymph node, and brain) of both nodular and superficial spreading melanomas and almost generally harbored mutations in either BRAF or NRAS genes." (PMID 22535842, 2012). "Such mutations have been documented in all subtypes of melanoma, including cutaneous (50–60% BRAF, 15% NRAS and 17% CKIT chronic sun damage), mucosal (11% BRAF, 5% NRAS and 21% CKIT) and uveal (50% GNAQ) melanomas." (PMID 21139585, 2011). "Melanomas share initiating genetic alterations such as oncogenic mutations in BRAF and NRAS and often show recurrent patterns of chromosomal aberrations." (PMID 22190975, 2011). "These cell lines are representative of different oncogenic events in melanoma and include 10 cell lines with a BRAF (BRAFV600E) and 7 cell lines with an NRAS (NRASQ61L or NRASQ61K) mutation." (PMID 21609436, 2011). "A recent manuscript reported on the direct antitumor effects of modulating AMPK in two melanoma cell lines, one with a BRAF mutation and another with an NRAS mutation." (PMID 21609436, 2011). "Given the pattern of p-AKT induction primarily in the non-NRAS mutant acquired resistant melanoma cell lines we focused on the effects of inhibiting the mTORC complexes or p70 S6K1." (PMID 22194965, 2011). "Further, we analyze the prognostic significance of NRAS in melanoma by stratifying our melanoma patients as follows: mutBRAF/wtNRAS, wtBRAF/mutNRAS, and wtBRAF/wtNRAS." (PMID 22039425, 2011). "We tested a combination of vemurafenib and metformin in a panel of melanoma cell lines with defined BRAF and NRAS mutations." (PMID 21609436, 2011). "The combination of the BRAF inhibitor vemurafenib (formerly PLX4032) and metformin were tested against a panel of human melanoma cell lines with defined BRAF and NRAS mutations for effects on viability, cell cycle and apoptosis." (PMID 21609436, 2011). "In the first trial, three of eight with advanced melanoma patients treated with AZD6244 achieved a partial response; BRAF and NRAS mutational status was unavailable." (PMID 22175026, 2011). "Cross-linked via NRAS, the MAP kinase cascade also initiates the PI3K and thereby the PI3K signaling pathway, another defective cascade found in a large percentage of melanomas." (PMID 22007305, 2011). "The effect of PLX4032 was tested on melanoma cells isolated from primary and metastatic lesions in which BRAF, NRAS and PTEN mutations were characterized." (PMID 20149136, 2010). "A genetic hallmark of human melanoma is mutually exclusive mutations of BRAF and NRAS, which are found in more than 90% of tumors." (PMID 20701798, 2010). "Seventy-one tumors were successfully assayed for common mutations activating the MAPK pathway in melanoma, i.e., BRAF exon 15 and NRAS exon 2 mutations." (PMID 20140953, 2010).
melanoma (continued). "PLX4032 promoted the proliferation of growth factor-dependent, NRAS mutant, primary melanoma cells, reduced cell adhesion and increased cell motility of highly proliferating, mitogen- independent advanced melanoma cells." (PMID 20149136, 2010). "The presence of ulceration is an important prognostic factor for melanoma even in stage III or metastatic disease and, therefore, we also assessed the associations between CDKN2A deletion and BRAF/NRAS mutation and ulceration." (PMID 20140953, 2010). "Activating mutations of the NRAS and BRAF genes occur in ∼20 and 50% of malignant melanomas respectively, and are almost always mutually exclusive." (PMID 20140953, 2010). "Our data indicates that targeting oncogenic NRAS-driven melanomas require decrease in both pERK and pAKT downstream of RAS-effectors for efficacy." (PMID 19492075, 2009). "The oncogenic potential of β-catenin was validated in a mouse model where stabilized β-catenin repressed p16Ink4a expression and together with an activated NRas, lead to melanoma development with high penetrance and short latency." (PMID 19234609, 2009). "In order to understand if other NRAS mutant lines employ similar signaling cascades downstream of NRAS, we chose to study SK-MEL-30, another melanoma line with an NRASQ61K mutant allele." (PMID 19492075, 2009). "In melanoma cells harboring an NRASQ61L or NRASQ61K mutant allele, we find that targeting NRAS alone or both BRAF and CRAF in combination or both BRAF and PIK3CA together showed efficacy." (PMID 19492075, 2009). "This review explores the molecular mechanisms regulating signaling pathways that may be potentially involved in modulating apoptosis in melanoma tumor cells harboring mutations in BRAF, NRAS, and NF1 genes." (PMID 42193039, 2026). "By analyzing morphological differences between melanocytes and melanoma, significant variations between the two cell lines may be captured to better define NRAS‐mutant melanoma, providing a route to develop targeted therapies." (PMID 41486569, 2026). "While some authors suggest that BRAF or NRAS mutations are obligatory initiating events, others have identified melanomas lacking these mutations yet harboring alterations in NF1 or other MAPK regulators." (PMID 41516405, 2026). "Further identification of differences between the two cell lines may aid in the development of biomarkers to better diagnose NRAS‐mutant melanoma." (PMID 41486569, 2026). "This disruption led to cell death, particularly in MAPKi-resistant NRAS-mutant melanomas." (PMID 41596686, 2026). "More than half (53.3%) of nevus–melanoma pairs shared identical MAPK driver mutations, consistent with prior sequencing studies showing that benign nevi frequently harbor BRAF or NRAS mutations and that a substantial fraction of melanomas retain the same driver mutation as their precursor." (PMID 41516405, 2026). "Poor patient prognosis of NRAS‐mutant melanoma may be partly attributed to its aggressive nature, hence the need for early diagnosis." (PMID 41486569, 2026). "In NRAS-mutant melanoma, compensatory ERK5 activation is accompanied by the induction of the Krüppel-like factors KLF2 and KLF4 but their role in MEKi resistance remains unclear." (PMID 41916083, 2026). "Melanomas can be further classified into four genomic subtypes based on the presence of specific driver mutations, namely B-Raf Proto-Oncogene (BRAF)-mutant, neuroblastoma RAS viral oncogene homolog (NRAS)-mutant, neurofibromatosis type I (NF1)-loss, and triple wild-type (TWT)." (PMID 40867277, 2025). "Over the past few decades, research has primarily focused on defining the genomic landscape of primary melanoma and metastatic disease, uncovering key genetic alterations, such as BRAF, NRAS, AKT1, and PTEN mutations, that shed light on melanoma progression and treatment resistance [3,4,]." (PMID 40669378, 2025).